CDH1 (cadherin 1)
Diseases named in the same sentence as CDH1 in open-access papers (continued):
Sharing a sentence is not in itself a finding about the gene and the disease.
melanoma (continued). "It has been shown to be able to downregulate SNAIL1 and consequently promote CDH1 expression, inhibiting melanoma cells’ ability to invade while miR-9 has been described either as an oncomiR or tumor suppressor in a variety of other cancers." (PMID 32013263, 2020). "Consistent with previous findings indicating rare E-cadherin (CDH1) mutations in cancer 33, only 2.7% of melanomas carry CDH1 mutations." (PMID 33204327, 2020). "We have recently reported that Cdh1 suppresses the BRAF/MEK/ERK signaling cascade in melanoma cells." (PMID 31420536, 2019). "miR-9 is able to downregulate SNAIL1 and consequently promote CDH1 expression, inhibiting melanoma cells’ ability to invade." (PMID 29112174, 2017). "The secretion of ISG15 by melanoma cells has been shown to modulate the phenotype of tumor-infiltrating DCs by inducing the expression of cadherin 1 (CDH1), which has been shown to reduce the migratory behavior of DCs in vitro." (PMID 27626310, 2016). "Using the extracellular matrix and adhesion molecule RT PCR Array analysis, we found that the expression of cadherin 1 was upregulated more than 10-fold in T++ melanoma cells." (PMID 26197340, 2015). "Within this cluster, however, most of the melanoma lines express VIM more strongly than CDH1, despite their low expression of migration-related genes." (PMID 22570691, 2012). "We chose NRAS over BRAF because there is more frequent CDH1 downregulation in NRAS-mutant melanomas and a lack of targeted therapies for NRAS-mutated cases." (PMID 40500450, 2025). "No melanoma developed within two years, indicating that Cdh1 loss alone is insufficient for tumour initiation." (PMID 40500450, 2025). "Oddly, the upregulation of CDH1 in metastatic tissues, while counterintuitive, may reflect heterogeneity of gene expression across melanoma tissues or may suggest plasticity during metastatic melanoma progression, thus requiring further validation." (PMID 40722520, 2025). "Of note, based on the microscopic analysis of mouse skin xenografts of SN-MM cells, we could identify a proliferation of MITFlow/CDH1−/CDH2+/ZEB1+/CD271+ melanoma cell clusters losing most melanocytic markers, thus suggesting a MIC identity, as proposed in CM." (PMID 38191367, 2024). "Moreover, A375P melanoma cells significantly increased the expression of CDH1 with concomitant down-modulation of CDH2 in the presence of hEo33-EV, with respect to cells exposed to hEo5-EV or left untreated." (PMID 39061080, 2024). "There are several subtypes of cadherins, however type I cadherins are the most relevant to melanoma, and include: epithelial cadherin (E-cadherin, CDH1), present in epithelial cells, melanocytes and keratinocytes; neural cadherin (N-cadherin, CDH2); and placental cadherin (P-cadherin, CDH3)." (PMID 37181747, 2023). "Two patients received gastrectomy due to a neuroendocrine tumor (NET), two patients presented with a mixed adenoneuroendocrine carcinoma (MANEC), one patient presented with a gastric metastasis of malignant melanoma, and one patient received prophylactic gastrectomy due to a CDH-1 gene defect." (PMID 36431318, 2022). "For RT‐PCR analyses, we chose melanophore marker genes pmel and mitf, neural crest markers sox10 and slug that can be reactivated in invasive melanomas, melanoma‐enriched genes bcl2 and axl, and cdh1 (E‐cadherin gene), of which expression was decreased in invasive melanomas." (PMID 35981147, 2022). "In addition, the ectopic expression of Cadherin 1 was associated with the downregulation of adhesion receptors, such as MCAM/MUC18 and β3 integrin subunit, resulting in suppression of melanoma cells invasion." (PMID 33980826, 2021). "Moreover, the enriched C2 contents jaeger metastasis dn is related to the molecular mechanisms of malignant melanoma progression and metastasis, and onder cdh1 targets 2 dn contributes to metastatic dissemination." (PMID 33922038, 2021). "CDH1 protein was highly expressed both in melanoma and normal skin biopsies(P<0.01)." (PMID 34308569, 2021).
melanoma (continued). "Dislike CDH1 being genetically deleted or epigenetically silenced during cancer development, those top-four cadherins were consistently expressed to form cell-cell contacts during the transition from melanocyte to melanoma." (PMID 33204327, 2020). "Moreover, other AP2-regulated genes, including CDH1 encoding E-cadherin and TIMP1 or TIMP2 encoding metallopeptidase inhibitors, are upregulated in melanoma cells after transfection with miR-214 precursors." (PMID 30866509, 2019). "Moreover, increased expression of miR-9-5p resulted in down-regulation of the NFKB-SNAIL pathway and simultaneously to up-regulation of CDH1 in melanoma cells." (PMID 24009496, 2013). "Cdh1 loss did not affect melanoma onset, primary tumour count or penetrance." (PMID 40500450, 2025). "We investigated the distinctive phenotype of these MITF−/low melanoma cells unveiling the loss of E-cadherin (CDH1) accompanied by concomitant increased expression of N-cadherin (CDH2), a feature associated with epithelial-to-mesenchymal transition (EMT) in various cancers including melanoma." (PMID 38191367, 2024). "Indeed, from the early stages of melanoma, there is a change in the CAM expression profile, which begins with a loss of E (epithelial)-cadherin (cadherin 1; CDH1) expression and associated loss of communication with the regulatory keratinocytes in the epidermis." (PMID 34439879, 2021). "Also, AMBRA1 expression negatively correlated with the expression of the mesenchymal genes CDH2, FN1 and VIM, whereas a positive correlation was evident for the epithelial marker CDH1, hence suggesting that an active EMT-like process is associated with low AMBRA1 expression in human melanoma cells." (PMID 33953176, 2021). "The LAMININ, FN1, ADGRE5, SPP1, MK, CDH1, and APP signals mainly originated from melanoma cells and were received by multiple cell types, suggesting that melanoma cells play extensive roles in the ecosystem." (PMID 41357561, 2025). "NFKB, CDH1, and ZEB1 are therefore potential master regulators for genes differentially expressed in melanoma microsatellites." (PMID 40717170, 2025). "Gene set enrichment analysis confirmed a metastatic signature in comparison to genes upregulated and downregulated in distant melanoma metastases, and identified pathway enrichment for NFKB, CDH1, and ZEB1 signaling." (PMID 40717170, 2025). "Following co-culture with hEo33, A375P cells exhibited increased levels of CDH1 while down-regulated CDH2, with respect to melanoma cells co-cultured with hEo5 or control." (PMID 39061080, 2024). "In this study, the results revealed a significant increase in the expression of the genes of CDH1 and MITF in AM, which strongly correlates with poor immunity in patients with melanoma." (PMID 38469735, 2024). "Of relevance, the microscopic analysis of the corresponding xenotransplants allowed the identification of clusters of MITF-/CDH1-/CDH2 + /ZEB1 + /CD271 + cells, supporting the existence of melanoma-initiating cells also in MM, as confirmed in clinical samples." (PMID 38191367, 2024). "When miR-22-3p is overexpressed in WM-266-4 melanoma cells, the cell viability is decreased, the expression levels of LGALS1, VIM, and SNAI2 are decreased, the expression level of CDH1 is increased, and cell apoptosis is increased." (PMID 39684214, 2024). "In turn, ZIC5 inhibition enhanced transcriptional elongation of CDH1 (E-cadherin), whereas ZIC5 overexpression triggered PDGFD-mediated activation of FAK and STAT3 signaling, thereby promoting melanoma aggressiveness." (PMID 36127329, 2022). "Among these hub genes, we identified the attenuated expressions of CDH1, COL17A1, DSG1, KRT14, and FLG in melanoma metastases compared with primary melanoma via bioinformatics analysis upon the GSE8401 and TCGA datasets." (PMID 35054979, 2022).
melanoma (continued). "As for EMT in other solid tumors, induction of ZEB, TWIST, and SNAIL transcription factor family members, as well as repression of the cell adhesion molecule E-cadherin (CDH1), are important for melanoma progression." (PMID 29215016, 2017). "Additionally, transition of normal melanocytic cells to malignant melanoma has a characteristic of EMT, which includes the disrupted adherens junctions resulted from the down-regulation of CDH1 and the up-regulation of CDH2." (PMID 39726752, 2024). "EBI3 was evidently highly-expressed in melanoma, and silencing of EBI3 could visibly suppress the survival and migration/invasion of melanoma cells, concurrent with the increased levels of BAX and CDH1 and the decreased expressions of BCL2 and CDH2." (PMID 39726752, 2024). "Our current study has hinted that EBI3 silencing could suppress the proliferation, migration and invasion of melanoma cells, concurrent with the diminished expression of CDH2 and BCL2 yet the upregulated expression of CDH1 and BAX." (PMID 39726752, 2024). "In addition, RTK (EGFR), E-cadherin (CDH1), and MITF are also involved in the transformation of normal melanocytes to benign moles, atypical hyperplasia moles, and melanoma." (PMID 35893303, 2022). "In vivo, in the metastatic model of melanoma, RNase A suppressed metastases in the lungs and changed the expression of EMT markers in the tissue adjacent to metastatic foci; this increased Cdh1 and decreased Tjp1, Fn and Vim, disrupting the favorable tumor microenvironment." (PMID 35745743, 2022). "Indeed, we observed changes in important EMT markers and regulators such as ZEB1, CDH1 (E-Cadherin), CDH2 (N-Cadherin), SNAI2, and TGFß1 in the MITF-KO cells as well as in TCGA melanoma samples." (PMID 33438577, 2021). "After 24-h GH treatment, SK-MEL-30 human melanoma cells showed a modest but significant increase of multiple EMT-related genes including mesenchymal markers ZEB-1, SNAI1, CLDN1 and SNAI2, while the epithelial marker CDH1 was significantly downregulated." (PMID 33291663, 2020). "CDH1 (E-cadherin) and CDH2 (N-cadherin) were also dominant in the melanoma cell pool." (PMID 33182777, 2020). "In the TCGA melanoma dataset, the top 312 genes with a positive correlation (down to Spearman r = 0.5) with the prototypic EMT marker ZEB1, were also positively correlated with SNAI1, NFATc2, CDH2, and AXL, but negatively with MITF and CDH1." (PMID 30710146, 2019). "Cell culture experiments have shown that monocyte-derived DCs can be activated by secreted ISG15 isolated from the media of melanoma cell lines, and that the addition of anti-ISG15 antibodies to the medium inhibited the expression of CDH1, a marker of DC activation." (PMID 27626310, 2016). "This upregulation was independent of the Tyr::Cre line or the Cdh1 melanoma model." (PMID 40500450, 2025). "While SNAI2 was shown to be positively correlated with MITF, the expression of CDH1 did not correlate with the expression of SNAI2 in the TCGA melanoma tumors which is consistent with the published findings in melanoma and melanocyte samples, despite CDH1 being a canonical target of SNAI2." (PMID 33438577, 2021). "In addition, the comparison of melanocytes with metastatic melanoma cells revealed a predominant expression of genes associated with interferon response and signaling via E-cadherin (CDH1) in melanocytes and genes involved in metastasis, EMT, and EGFR-signaling in melanoma." (PMID 32878000, 2020). "QRT-PCR experiments showed that naïve 501mel melanoma cells exposed to the secretome of melanoma cells rendered senescent by MITF silencing exhibited an increased level of SNAIL1, TWIST1, Fibronectin1, N-Cadherin (CDH2) mRNAs whereas MITF and E-Cadherin (CDH1) transcripts were markedly decreased." (PMID 24344100, 2013).
melanoma (continued). "That inference however applies only to those cell lines (the majority) that show an inverse expression: VIM high, CDH1 low; it does not apply to the leukemia lines nor to at least 2 of the melanoma lines, for which no clear epithelial/mesenchymal assignment can be made based on CDH1/VIM ratio." (PMID 22570691, 2012). "Additionally, EMT-related signaling pathways, including CDH, CDH1, WNT, Laminin, Collagen, and Tenascin, were more active in CCNB1-high melanoma, with both incoming and outgoing signaling interactions strengthened, whereas these signals weakened in CCNB1-low melanoma." (PMID 40430484, 2025). "Recently, a report suggested that the knockdown of AHNAK in a melanoma cell line led to the loss of cadherin-1 and was associated with poor patient outcomes, providing evidence that upregulated RNF38 induced a reduction in E-cadherin levels rather than directly interacting with E-cadherin." (PMID 30836988, 2019). "Finally, MGPT also led to the identification of SFs, such as two PVs in CDH1 and one PV in CDKN2A in BC patients without a personal/family history suggestive of hereditary diffuse gastric cancer or melanoma and pancreatic carcinoma syndrome, respectively." (PMID 40361347, 2025).
hepatocellular carcinoma (279 papers, 1994 to 2026). A malignant tumor that arises from hepatocytes. "SIRT6 has been reported to decrease E-cadherin (encoded by the CDH1 gene) in normal or hepatocellular carcinoma cell lines through the deacetylation of Beclin 1, a key regulator of autophagy, and the promotion of autophagy-mediated E-cadherin degradation." (PMID 36831330, 2023). "HELLS binds to the NFR of CDH1, which encodes E-cadherin and silences CDH1 at the epigenetic level in hepatocellular carcinoma, thus contributing to EMT and cancer metastasis." (PMID 35965507, 2022). "Further study suggested that the CDH1 (E-cadherin) promoter region of the HCV core protein(+) Huh-7 cells becomes substantially hypermethylated, and the reduced CDH1 protein expression in hepatocellular carcinoma patients was associated with poor prognosis." (PMID 34512600, 2021). "In hepatocellular carcinoma cell lines, decreased levels of miR-23b are correlated with the loss of expression of CDH1." (PMID 26622315, 2015). "Here, we showed that an Alu element in lnc-APUE could base-pair with the Alu element in 3'-untranslated region of E-cadherin coding gene (CDH1), triggering CDH1 mRNA decay and E-cadherin loss, consequently enhancing hepatoma cell migration and invasion." (PMID 41632098, 2026). "In addition to Cdh1, other cytoskeleton-related genes are silenced by DNA hypermethylation, e.g., Connexin26 in rat hepatocellular carcinomas is induced by choline-deficient diets, and Cdh13 hypermethylation (CADHERIN-13) correlates negatively with hormone receptor status in breast cancers." (PMID 34681626, 2021). "SphK1 facilitated autophagy and induced the EMT by promoting lysosomal degradation of CDH1/E-cadherin in hepatoma cells." (PMID 36909198, 2023). "The results of our previous study also revealed that TRERNA1 promotes hepatocellular carcinoma (HCC) metastasis via recruitment of the EHMT2/SNAI1 complex to suppress CDH1." (PMID 35031597, 2022). "Previous reports validated the transcriptional regulation of SNAIL and TWIST1 by miR-370-3p in hepatocellular carcinoma, thereby suppressing metastasis, as well as CDH1 by miR-421 in HNSCC, thereby promoting cell invasion and proliferation." (PMID 36686733, 2022). "The transcription factors SNAIL, TWIST, and ZEB1/2 are known to bind the enhancer boxes (E-box) of Cdh1, attracting epigenetic complexes and silencing its expression, reaching 30% of hepatocellular carcinoma cases with silenced Cdh1." (PMID 34681626, 2021). "The epigenetic regulation of genes involved in EMT and in mesenchymal to epithelial transition (MET), such as cadherin 1 (CDH1), has been extensively documented in a number of malignancies, including breast and hepatocellular carcinomas." (PMID 29739810, 2018). "Additionally, NAT10 knockdown was found to significantly upregulate the expression of the EMT marker cadherin 1 (E‐cadherin) and downregulate vimentin expression in hepatocellular carcinoma cells, inhibiting invasion and migration in vitro." (PMID 39764566, 2025). "Similarly, a prior study revealed that lncRNA TRERNA1 was able to recruit EHMT2 onto the CDH1 promoter region to promote hepatocellular carcinoma development." (PMID 35419917, 2022). "In hepatomas cells, sphingosine kinase 1 (SPHK1) could induce EMT and promote cell invasion by enhancing the K63-linked ubiquitination of BECN1, thus accelerating CDH1/E-cadherin lysosomal degradation." (PMID 31272261, 2019). "Elevated TUFT1 expression regulates CDH1 and vimentin expression through the hypoxia-inducible factor 1–SNAI1 signaling pathway in pancreatic and hepatocellular cancer metastasis." (PMID 34455105, 2021). "In hepatoma cells, HDACs catalyze H3K4/56 deacetylation at the CDH1 promoter, inducing E-cadherin repression by Snail2, in favor of EMT." (PMID 33803458, 2021). "Additionally, our current study demonstrates the clinical relevance of PAH and Cdh1 correlation in hepatocellular carcinoma (HCC)." (PMID 33260674, 2020).
hepatocellular carcinoma (continued). "In our present in vitro study, the mRNA expression level of SIP1, but not those of Snail or Twist, showed a significant inverse correlation with that of CDH-1, which is in agreement with previous findings in HNSCC, breast, and hepatocellular carcinoma cells." (PMID 24887090, 2014). "For several loci the frequency of aberrant hypermethylation is indistinguishable from conventional hepatocellular carcinoma arising in the non-cirrhotic liver, whereas for the APC and the CDH1 gene statistically significant differences in hypermethylation could be found." (PMID 21060828, 2010).